ABCG1 (ATP binding cassette subfamily G member 1)
Diseases named in the same sentence as ABCG1 in open-access papers (continued):
Sharing a sentence is not in itself a finding about the gene and the disease.
atherosclerosis (continued). "Specifically, bone marrow-recipient mice with Abca1 and Abcg1 knockout mice exhibited accelerated atherosclerosis and extensive infiltration of the myocardium and spleen with foamy cell macrophages." (PMID 39857239, 2024). "At the current time point, ABCG1 is known to be involved in the cross-talk of lipid transport, metabolism, and the innate immune system, with implications for the development of atherosclerosis, diabetes mellitus, and lung disease." (PMID 39857239, 2024). "Research suggests that diminished functions of ABCA1 and ABCG1 result in cholesterol accumulation within cells and contribute to atherosclerosis development." (PMID 38474781, 2024). "Together, our data demonstrate that LXN ablation upregulates the expression of ABCA1 and ABCG1 in macrophages in vitro or atherosclerosis in vivo." (PMID 39424784, 2024). "These genes are involved in cholesterol metabolism (Abca1, Abcg8, Abcg5, Lpl, Cyp7a1, and Pltp), lipid and atherosclerosis (Abca1, Il1b, Ccl2, and Abcg1), bile secretion (Abcg8, Abcg5, and Cyp7a1), and IL-17 signaling pathway (Ccl7, Il1b, and Ccl2)." (PMID 37301941, 2023). "Hypermethylation of ABCG1 results in a decrease in gene expression, which is associated with cholesterol metabolism disorders, impaired insulin secretion, and accelerated foam cell formation, and may contribute to type 2 diabetes mellitus, metabolic syndrome, and atherosclerosis CVDs." (PMID 37507725, 2023). "The role of Abca1, Abcg1, and Pltp in foam cells is particularly apparent in the late stage of atherosclerosis." (PMID 36910156, 2023). "Our study showed that, among the target genes of LXRα, key lipid processing genes including Abcg1, Lpl, Pltp, and Abca1 have a strong positive correlation with atherosclerosis." (PMID 37301941, 2023). "Upregulation of ABCA1 and ABCG1 expression can inhibit macrophage-derived foam cell formation and thereby effectively reduce the onset and progression of atherosclerosis." (PMID 36923537, 2023). "Binding of ligand to LXRα results in the upregulation of ABCA1 and ABCG1 transcription in macrophages, enhancement of cholesterol efflux, and inhibition of atherosclerosis progression." (PMID 36713845, 2023). "Future studies should be devoted to testing if ABCG1 deletion within the VSMC of atherogenic mouse models results in exacerbating atherosclerosis." (PMID 37887863, 2023). "ABCG1 prevents the accumulation of excessive cholesterol in the human body and thus prevents the build-up of atherosclerosis." (PMID 37507725, 2023). "LXR agonists promote reverse cholesterol transport via ABCA1 and ABCG1, protecting against atherosclerosis." (PMID 36768382, 2023). "A traditional Chinese medicine Yin‐xing‐tong‐mai decoction (YXTMD) has been used to treat atherosclerosis by activating the PPARγ‐LXRα‐ABCA1/ABCG1 pathway to enhance cholesterol efflux." (PMID 37324843, 2023). "The regulation of the functional activity of ABCA1 and ABCG1 and their disorders are also of clinical interest and are a promising target for the treatment of atherosclerosis." (PMID 36363640, 2022). "LXR also plays an important role in RCT by regulating several transporters including ABCA1 and ABCG1, so can help to reduce cholesterol and atherosclerosis." (PMID 36159325, 2022). "In an in vitro atherosclerosis cell model, allicin, leonurine, etc. have been shown to promote lipid efflux through the PPARγ-LXRα-ABCG1 axis." (PMID 35432274, 2022). "Some related studies have shown that the ABCG1 gene is itself a direct target of LXRα and LXRα is a selective target of PPARγ in the context of atherosclerosis." (PMID 35432274, 2022). "ABCA1 has been shown to be causally involved in reverse cholesterol transport, and combined deletion of ABCA1 and ABCG1 in mouse macrophages dramatically impaired cholesterol efflux to ApoA-I, accelerated atherosclerosis, and promoted foam cell accumulation." (PMID 36077004, 2022).
atherosclerosis (continued). "Among the different processes in which miR-199a-5p participate, several targets are implicated in atherosclerosis including ABCA1, ABCG1, Cav-1, HIF1A, CD38, NCOR1, and SIRT1 in human and mouse." (PMID 36407436, 2022). "In summary, the present study has demonstrated a protective role for asprosin in macrophage lipid accumulation and atherosclerosis development and revealed a novel mechanism underlying the modulation of ABCA1 and ABCG1 expression." (PMID 35902881, 2022). "Previous studies have demonstrated a crucial role for PPARγ in the induction of ABCA1/ ABCG1 expression, and the prevention of foam cell formation and atherosclerosis progression." (PMID 35590369, 2022). "Reduced lipid-exporting function of ABCA1 and ABCG1 in vascular wall macrophages is one of the key links to foam cell formation and progression of atherosclerosis." (PMID 35897703, 2022). "Studies from our groups and others have revealed that increased ABCA1 and ABCG1 expression contributes to alleviation of lipid accumulation and atherosclerotic lesions in atherosclerosis-prone mice." (PMID 33692340, 2021). "This happens via induction of the ATP-binding cassette transporters ABCA1 and ABCG1, which initiate macrophage reverse cholesterol transport and prevent atherosclerosis." (PMID 34868038, 2021). "Research findings suggested that ABCA1 and ABCG1 are key transporters that facilitate cholesterol egress from macrophages, reducing atherosclerosis development." (PMID 34445501, 2021). "SDT with 5-aminolevulinic acid as a sonosensitizer (ALA-SDT) activates the PPAR-γ-LXRa/ABCA1 and ABCG1 pathway, increasing cholesterol efflux, induces an anti-inflammatory response, and ultimately reduces the signs of atherosclerosis." (PMID 34940525, 2021). "In summary, the present study has demonstrated a novel role of macrophage CTRP12 in inhibiting the development of atherosclerosis and uncovered a novel mechanism underlying the regulation of ABCA1 and ABCG1." (PMID 33692340, 2021). "Here we review the available data on the expression of ABCA1, ABCG1 and SR-B1 in patients with atherosclerosis, CVD, and animal models of atherosclerosis." (PMID 34940525, 2021). "Consistently, ablation of macrophage ABCA1 and ABCG1 in mice resulted in a substantial increase in atherosclerosis progression." (PMID 34445501, 2021). "This review summarizes the progress in studying the genomic variants of ABCA1, ABCG1, and SCARB1, and the regulation of their function at transcriptional and post-transcriptional levels in atherosclerosis." (PMID 34940525, 2021). "The decrease in the transcription level of ABCG1 under the influence of various lncRNAs is one of the ways to form the foam cells from VSMCs and, thus, contributes to the pathogenesis of atherosclerosis." (PMID 34940525, 2021). "We and others previously reported that administration of leonurine, kuwanon G or dihydromyricetin inhibits lipid accumulation in THP-1 macrophages and protects against atherosclerosis in mice by activating the LXRα-ABCA1/ABCG1 signaling pathways." (PMID 33692340, 2021). "Baicalin potentially exerts anti-atherosclerosis effects through the PPARγ–LXRα–ABCA1/ABCG1 pathway by promoting cholesterol efflux from macrophages and delaying the formation of foam cells." (PMID 33321972, 2020). "According to the TargetScan7.2 database, mir-17a-5p and mir-18a are associated with ATP-binding cassette transporter A1 (ABCA1) and ATP-binding cassette transporter G1 (ABCG1), which are the important factors in atherosclerosis." (PMID 32908568, 2020). "Activation of the PPARγ/LXRα signaling pathway has been shown to increase ABCA1 and ABCG1 expression and thereby mitigate atherosclerosis." (PMID 33959213, 2020).
atherosclerosis (continued). "There are few studies investigating direct associations between DNA methylation of ABCG1 and APOE and ischemic stroke and atherosclerosis." (PMID 31823830, 2019). "Our results showed that overexpression of salusin-α increased the expression of positive regulators of atherosclerosis (ABCA1 and ABCG1) and inhibited negative regulators of atherosclerosis (ACAT1 and CD36)." (PMID 30105261, 2018). "The Tall group has extensively described the protective role of the LXR target genes Abca1, Abcg1, and Apoe in hematopoietic cell types, and their contributions to atherosclerosis." (PMID 30087224, 2018). "Downregulation of ABCG1 and ABCA1 has been associated with reduced cholesterol efflux and has been shown to increase the risk of atherosclerosis." (PMID 29643945, 2018). "Because of the important role of Abcg1 in maintaining tissue lipid homeostasis, especially in macrophages, Abcg1 was proposed to protect from atherosclerosis development by promoting cholesterol efflux to HDL from arterial macrophages." (PMID 28869506, 2017). "Nevertheless, it is now well-approved that ABCA1, ABCG1, and SR-BI represent three major key players in atherosclerosis." (PMID 27252658, 2016). "Although cholesterol lowering is a way to decrease lipid retention, increasing lipid efflux from macrophages, mostly through ABCA1 and ABCG1, has been regarded as another significant strategy to limit atherosclerosis." (PMID 24999295, 2014). "Overexpression of ABCA1 and ABCG1 limits atherosclerotic plaque formation, while genetic deletion of these genes promotes foam cell formation and accelerates atherosclerosis in animal models." (PMID 24999295, 2014). "Several ATP-binding cassette (ABC) transporters, including ABCG1, have been involved in macrophage sterol homeostasis, reverse cholesterol transport, and atherosclerosis." (PMID 24972087, 2014). "Murine models of atherosclerosis, using ABCG1-apoE double knock out, showed markedly defective cholesterol efflux and increased macrophage apoptosis." (PMID 23781332, 2013). "Although there is no firm consensus, some preclinical studies support a role for ABCG1 in atherosclerosis in specific animal models." (PMID 22649448, 2012). "PPARγ is also closely clustered with P8, PPARβ, and ABCG1 which are well-known for their roles in atherosclerosis." (PMID 18237428, 2008). "This study thereby proposes that the progression of atherosclerosis may be modulated by USP18 through its regulation over ABCG1 expression." (PMID 39804798, 2025). "Collectively, SMC-Abca1/Abcg1 deficiency did not affect atherosclerosis or plaque composition in the aortic root or BCA." (PMID 39931819, 2025). "This could account for the reduced activity of ABCA1 and ABCG1, clarifying the pathophysiology of atherosclerosis and potential therapeutic targets." (PMID 41300518, 2025). "PPAR-γ/LXR, the key pathway known to regulate the expression of ABCA1/ABCG1, has been identified could enhance cholesterol efflux, thereby attenuating atherosclerosis." (PMID 40537740, 2025). "Moreover, the expression of the ABCG1 gene has been shown in mice to be integral to cellular efflux of cholesterol and prevention of atherosclerosis, a common comorbidity of T2D." (PMID 40356723, 2025). "Recently, Zulong found visceral adipose tissue‐derived exosomes in high‐fat diet‐fed obese mice promoted macrophage foam cell formation and M1 macrophage transition, decreased macrophage‐regulated cholesterol efflux via downregulation of ABCA1 and ABCG1, and further exacerbated atherosclerosis." (PMID 40045164, 2025). "However, in late disease a decreased expression of Abcg1 leads to reduced atherosclerosis due to increase macrophage apoptosis." (PMID 39088185, 2024). "Importantly, T0901317 significantly stimulated atherosclerosis susceptibility, despite an associated increase in the macrophage gene expression levels of cholesterol efflux transporters ABCA1 and ABCG1." (PMID 38672446, 2024).
atherosclerosis (continued). "As the major contributors to cholesterol efflux, ABCA1 and ABCG1 are responsible for approximately 70% of cholesterol release from lipid‐rich macrophages, thereby playing a critical role in protecting against macrophage lipid accumulation and atherosclerosis." (PMID 39698913, 2024). "Here we report an investigation to establish if microinjection of site-specific nucleases directly into zygotes prepared from the REVERSA could be used to investigate the role of the ATP binding cassette transporter G1 (ABCG1) in atherosclerosis regression." (PMID 39088185, 2024). "In addition to activating PPARα signaling, many TCM prescriptions stimulate PPARγ–liver X receptor (LXR) α–ABCA1/ABCG1 signaling pathways, thereby ameliorating lipid profiles and atherosclerosis through upregulation of reverse cholesterol transport (RCT)." (PMID 38699583, 2024). "It is possible that in our study, the ubiquitous loss of Abcg1 lead to a pro-atherogenic effect in macrophages that was counterbalanced by an enhanced Treg mediated atherosclerosis regression, resulting in no overall change in plaque area." (PMID 39088185, 2024). "Furthermore, 5-aminolevulinic acid-mediated sonodynamic therapy improves cholesterol efflux via activating PPARγ–LXRα–ABCA1/ABCG1 signaling pathways, enhancing efferocytosis and cholesterol efflux, and eventually ameliorating atherosclerosis." (PMID 38699583, 2024). "Similarly, 12-Hydroxyeicosapentaenoic acid reduces foam cell formation and atherosclerosis via activation of PPARγ–ABCA1/ABCG1 signaling pathways." (PMID 38699583, 2024). "Clinical and pre-clinical evidence suggest that ABCG1 has a role potential role in atherosclerosis." (PMID 39088185, 2024). "Due to its lipid transport function, ABCG1 may contribute to the prevention of atherosclerosis and is involved in the functioning of the lung, pancreas, and other organs and systems." (PMID 39857239, 2024). "Especially in atherosclerosis, the role of ABCG1 is demonstrated to be complex." (PMID 38896016, 2024). "Thus, ABCG1, being involved in cholesterol transport, represents an interesting target for investigation in atherosclerosis." (PMID 39857239, 2024). "A single deficiency of ABCA1 or ABCG1 in macrophages has been reported to not increase atherosclerosis, probably because ABCA1 deficiency leads to upregulation of ABCG1 expression." (PMID 36904298, 2023). "The ABCA1 and ABCG1 membrane transporters participate in cholesterol transport outside of any cell type and favor the increase in HDL synthesis in hepatocytes, therefore a deficiency of these transporters promotes accelerated atherosclerosis." (PMID 37754229, 2023). "Since the formation of macrophage foam cells is influenced by the balance between modified LDL uptake and cholesterol efflux, we investigated the effects of SFN on cholesterol efflux and the expression of ABCA1 and ABCG1 in this atherosclerosis-prone genetic mouse model." (PMID 37432260, 2023). "The membrane transporters ABCA1 and ABCG1 are involved in the reverse transport of cholesterol and stimulate the HDL synthesis in hepatocytes, therefore the deficiency of these transporters promotes the acceleration of atherosclerosis." (PMID 37754229, 2023). "However, the effect of cholesterol efflux pathways mediated by ATP-binding cassette A1 and G1 (ABCA1/ABCG1) on T cell-dependent age-related inflammation and atherosclerosis remains poorly understood." (PMID 35778407, 2022). "Studies from our group and others have demonstrated that astragalin, C1q tumor necrosis factor-related protein 12, fargesin and biochanin A increase RCT efficiency and protect against atherosclerosis in apolipoprotein E-deficient (apoE−/−) mice by up-regulating ABCA1 and ABCG1 expression." (PMID 35902881, 2022).
atherosclerosis (continued). "These and other data identified an important role of ABCG1 in the prevention of atherosclerosis, which allows us to consider ABCG1 along with ABCA1 as potential therapeutic targets for the prevention of atherosclerosis through the regulation of their expression, localization, and degradation." (PMID 36363640, 2022). "Free cholesterol is either effluxed from cells to HDL (reverse cholesterol transport) via the lipid transporters ABCA1 and ABCG1, key players in atherosclerosis, or trafficked to the ER, where it is reconverted into cholesteryl esters and stored in lipid droplets." (PMID 34876704, 2022). "However, a study in a mouse atherosclerosis model revealed that PPARγ knockout mice exhibited enlarged atherosclerotic plaques, which is related to the suppression of ABCG1 expression." (PMID 35432274, 2022). "Surprisingly though, studies involving the whole-body and tissue-specific deletion and overexpression of ABCA1 and ABCG1 have been conflicting when evaluating whether these two transporters protect against atherosclerosis." (PMID 35625607, 2022). "For example, in atherosclerosis, PPARγ promotes the expression of CD36, causing enhanced uptake of lipids by macrophages; it also accelerates cholesterol efflux by upregulating the expression of ABCA1 and ABCG1." (PMID 35432274, 2022). "Importantly in relation to atherosclerosis, genes related to lipid metabolism, which featured in resident macrophages, were downregulated (Plin2, Trem2, Lipa, Msr1, and Abcg1) by CLEC4A2 deletion." (PMID 35017526, 2022). "Indeed, in patients with atherosclerosis, the mRNA level of ABCG1, and the content of ABCG1 in blood macrophages, are significantly reduced compared with controls." (PMID 34940525, 2021). "Studies from our group and others have revealed that angiopoietin-1, pregnancy-associated plasma protein-A, and homocysteine inhibit ABCA1- and ABCG1-dependent cholesterol efflux from lipid-loaded macrophages and aggravate atherosclerosis in apoE−/− mice by downregulating LXRα expression." (PMID 33692340, 2021). "Furthermore, ox-LDL activated LXRs promote the outflow of cholesterol via upregulating transporters, such as ABCA1 and ABCG1, in macrophages, thereby alleviating atherosclerosis." (PMID 34026849, 2021). "LXRβ activation is sufficient to reduce atherosclerosis and may contribute, together with LXRα, to the favorable upregulation of Abca1 and Abcg1 expression both in vivo and in vitro." (PMID 33233455, 2020). "In this study, we evaluated the associations between DNA methylation at ABCG1 (cg06500161 and cg02494239) and APOE (cg14123992) and ischemic stroke and early examinations of atherosclerosis (including cIMT, ABI, and baPWV) in subjects from a family-based study." (PMID 31823830, 2019). "Interestingly, we found CpG sites in proximity to the gene ABCG1, which has been associated to body mass, triglycerides, HDL-C, atherosclerosis, and type 2 diabetes in EWAS, among our nominally significant MetS CpGs." (PMID 31796056, 2019). "ABCG1 is expressed ubiquitously and is functional in the context of atherosclerosis." (PMID 31159502, 2019). "Recently, the pharmacologic suppression of hepcidin has been shown to increase the expression of ABCA1 and ABCG1 and lipid efflux via the macrophage-specific expression of cholesterol efflux transporters and to reduce foam cell formation and atherosclerosis in vivo and vitro." (PMID 30373612, 2018). "Westerterp et al72 demonstrate that deficiency of ABCA1/ABCG1 in endothelial cells accelerates atherosclerosis, and they suggested that endothelial cell–derived ABCA1/ABCG1 plays a role in preservation of endothelial NO synthase activity and suppression of endothelial inflammation." (PMID 29437605, 2018).